GRM6 (glutamate metabotropic receptor 6)
Description:
G protein-coupled receptor for glutamate. Ligand binding causes a conformation change that triggers signaling via guanine nucleotide-binding proteins (G proteins) and modulates the activity of down-stream effectors, such as adenylate cyclase. Signaling inhibits adenylate cyclase activity (By similarity). Signaling stimulates TRPM1 channel activity and Ca(2+) uptake. Required for normal vision.
Synonyms: mGluR6; GPRC1F; mGlu6; CSNB1B
Tractability: Small molecule: a high-quality ligand is known; it belongs to a druggable protein family. Antibody: UniProt places it where antibodies can reach, with high confidence; its Gene Ontology location is reachable by antibodies, with high confidence; UniProt predicts a signal peptide or a membrane-spanning region. PROTAC: a small molecule that binds it is known.
Target class: Family C G protein-coupled receptor; Metabotropic glutamate receptor; Small molecule receptor (family C GPCR); Membrane receptor; Neurotransmitter receptor (family C GPCR)
Gene: Protein-coding gene on chromosome 5 (178,977,587 to 178,996,206, reverse strand). Ensembl gene ENSG00000113262.
Subcellular location: Cell membrane; Endoplasmic reticulum membrane; Golgi apparatus membrane; Cell projection, dendrite
Pathways (Reactome):
Signal Transduction: Class C/3 (Metabotropic glutamate/pheromone receptors); G alpha (i) signalling events
Gene Ontology:
Molecular function: glutamate receptor activity; protein binding; protein homodimerization activity; adenylate cyclase inhibiting G protein-coupled glutamate receptor activity; G protein-coupled receptor activity
Biological process: detection of light stimulus involved in visual perception; G protein-coupled glutamate receptor signaling pathway; positive regulation of calcium ion import across plasma membrane; detection of visible light; regulation of synaptic transmission, glutamatergic; adenylate cyclase-inhibiting G protein-coupled glutamate receptor signaling pathway; chemical synaptic transmission; G protein-coupled receptor signaling pathway; locomotory behavior; sensory perception of light stimulus
Cellular component: endoplasmic reticulum membrane; Golgi membrane; plasma membrane; cell tip; dendrite; membrane; new growing cell tip; synapse
Genetic constraint (gnomAD): Loss-of-function variants: 72 observed, 71.27 expected, observed/expected ratio (o/e) 1.01, 90% interval 0.83 to 1.23. The upper end of that interval is the gene's LOEUF score, 1.23, which puts it in group 5 of 6, group 1 being the genes least tolerant of losing a copy. Missense variants: 1,229 observed, 1,132.7 expected, observed/expected ratio (o/e) 1.09, 90% interval 1.03 to 1.14. Synonymous variants: 565 observed, 486.73 expected, observed/expected ratio (o/e) 1.16, 90% interval 1.08 to 1.24.
Homologues: Orthologues: chimpanzee GRM6 (99% identical), macaque GRM6 (98% identical), dog GRM6 (95% identical), pig GRM6 (95% identical), rabbit GRM6 (94% identical), mouse Grm6 (93% identical), rat Grm6 (93% identical), guinea pig GRM6 (85% identical), tropical clawed frog grm8l (74% identical), zebrafish grm6b (73% identical), zebrafish grm6a (73% identical), Drosophila melanogaster mGluR (45% identical). Paralogues in human: GRM8 (69% identical), GRM4 (68% identical), GRM7 (66% identical), GRM2 (45% identical), GRM3 (45% identical), GRM1 (40% identical), GRM5 (40% identical).
Diseases named in the same sentence as GRM6 in open-access papers:
GRM6 is named in the same sentence as 29 diseases in open-access papers, as found by Europe PMC text mining. Sharing a sentence is not in itself a finding about the gene and the disease. The quoted sentences say what the papers report.
congenital stationary night blindness (15 papers, 2009 to 2025). "We noted heterozygous variants in two genes known to cause congenital stationary night blindness (CSNB): GRM6 (c.2092 C > G: p.(L698V)) and TRPM1 (c.3958 G > A: p.(E1320K))." (PMID 33776059, 2021). "Mutations in the glutamate receptor metabotropic 6 gene (GRM6) have been identified in patients with congenital stationary night blindness (CSNB1B)." (PMID 19862333, 2009). "Pseudodominant inheritance has already been documented in retinal disorders, including congenital stationary night blindness (CSNB) with alterations in the GRM6 gene, in patients with RP related to IMPG2 variants, or in cone-rod dystrophy and Stargardt disease with ABCA4 pathogenic variants." (PMID 36832217, 2023). "However, GRM6 variants are inherited in an autosomal recessive manner, and they have been described to lead to a different clinical phenotype (congenital stationary night blindness)." (PMID 37107692, 2023). "Mutations in the GRM6 gene, which encodes mGluR6, are associated with congenital stationary night blindness (CSNB) in humans, and both human patients and mouse models in which mGluR6 is ablated exhibit a lack of b-wave in electroretinograms, indicating ON-BC disfunction." (PMID 34793838, 2021). "Huynh and co-workers (2014) reported a case of a female patient with STGD1 and complete congenital stationary night blindness (CSNB1B), carrying biallelic ABCA4 variants (p.(Leu1201Arg) and p.(Arg2077Gly)) along with biallelic GRM6 gene variants (c.50_64del and c.1835_1837del)." (PMID 40269797, 2025). "These systemic syndromes can be caused by a series of genes, including NYX, CACNA1F, GRM6, and LRIT3, responsible for congenital stationary night blindness (CSNB); COL2A1, COL11A1, COL9A1, and COL9A2, responsible for Stickler syndrome; and FBN1, responsible for Marfan syndrome." (PMID 36980859, 2023). "GRM6 and TRPM1 are bipolar DEGs and their mutations could cause a recessive congenital stationary night blindness (CSNB), a condition due to abnormal photoreceptor-bipolar signaling." (PMID 31848347, 2019). "In humans, mutations in the mGluR6 gene (GRM6) have been linked to congenital stationary night blindness, characterized in the electroretinogram by the absence of an ON response." (PMID 22523578, 2012).
retinal degeneration (8 papers, 2017 to 2023). Degeneration of the retina. "We have previously demonstrated that the intravitreal injection of AAVs carrying the Opto-mGluR6 optogene under the control of the ON-BPC-specific GRM6 promoter can restore visual function in otherwise blind retinal degeneration (rd1) mice." (PMID 40838063, 2023).
myopia (5 papers, 2009 to 2025). "The GRM6 variants, rs762724 and rs2067011, were reported to have an association with higher myopia in the Han Chinese population." (PMID 38609494, 2024). "Many patients with cCSNB are found to have myopia, especially in those patients carrying with GRM6 and NYX mutations." (PMID 38448886, 2024). "Two other mGluR variants, Glu receptor 6 (GRM6) rs762724 and rs2067011, were reported to have an association with higher myopia in the Han Chinese population." (PMID 37964012, 2023). "This study tested if any mutations in GRM6 were solely responsible for high myopia." (PMID 19862333, 2009). "Similarly, moderate to high myopia is also a common sign in CSNB1B patients with GRM6 mutations." (PMID 19862333, 2009). "Early-onset myopia was more common in patients with mutations of NYX, GRM6, and TRPM1 than in patients with CACNA1F mutations, further supporting the link between the mGluR6 signaling pathway and myopia." (PMID 38448886, 2024). "Upon complete analysis of GRM6 in 96 patients with high myopia, four novel variations predicted to have potential functional consequence were identified: c.67-82delCAGGCGGGCCTGGCGCinsT (p.Gln23_Arg28delinsCys), c.858-5a>g (r.spl)?" (PMID 19862333, 2009). "The authors suggested that the identification of rare variants in GRM6 in patients with high myopia may indicate a role for GRM6 in myopia development." (PMID 41153400, 2025). "Sequence variations in GRM6 detected in 96 high myopia patients." (PMID 19862333, 2009). "This was the first sequencing evaluation of GRM6 in a group of patients with high myopia." (PMID 19862333, 2009). "In this study, we analyzed the genomic sequence of GRM6 in 96 Chinese patients with high myopia." (PMID 19862333, 2009). "Myopia is not always associated with CSNB, except in cases resulting from mutations in NYX and GRM6, suggesting a gene-specific phenotype rather than association with night blindness." (PMID 19862333, 2009).
autosomal recessive congenital stationary night blindness (2 papers, 2024 to 2025). "Mutations in Grm6 gene in humans lead to autosomal recessive congenital stationary night blindness (arCSNB)." (PMID 39754206, 2025). "Variants in GRM6 cause autosomal recessive congenital stationary night blindness, which is different from the clinical diagnosis in this proband." (PMID 38184646, 2024).
cone-rod dystrophy (2 papers, 2023 to 2024). Inherited retinal dystrophies that belong to the group of pigmentary retinopathies.
heroin addiction (2 papers, 2018 to 2020). "Regarding the variants in genes involved in the glutamatergic synapse, GRIN3A and GRM6 were two candidate genes related to heroin addiction and response to MMT, respectively." (PMID 30059533, 2018). "Glutamate receptor metabotropic 6 (GRM6) and tryptophan hydroxylase 2 (TPH2) have also been reported to be involved in heroin dependence." (PMID 30059533, 2018).
Stargardt disease (2 papers, 2017 to 2023). "Recently, a rare combination of mutations in ABCA4 and GRM6, genes whose mutations are associated with more than one form of retinal dystrophies, was reported in a patient with atypical Stargardt disease." (PMID 28912962, 2017).
amblyopia (1 paper, 2022). Decreased vision that results from abnormal visual development. "Those with the GRM6, TRPM1, or CACNA1F variants had both amblyopia and nystagmus." (PMID 36499293, 2022).
autism spectrum disorder (1 paper, 2016). A spectrum of developmental disorders that includes autism, and Asperger syndrome. "GRM6 and GRM8, the paralogs of GRM7, have been implicated in neurodevelopmental diseases such as attention deficit hyperactivity disorder (ADHD) and autism spectrum disorders (ASD)." (PMID 27435318, 2016).
ciliopathy (1 paper, 2022). A genetic disorder of the cellular cilia or the cilia anchoring structures, the basal bodies, or of ciliary function. "Eight of the 140 potential ciliopathy genes had predicted secondary interaction with gold standard cilia proteins, Aplnr, Casr, Gcgr, Grm6, Med1(or Mbd4), Mlh1, Rxfp2, and Wdr62.." (PMID 36456625, 2022). "In addition, 7 genes had primary interactions with the 24 directly interacting potential ciliopathy genes and thus had secondary interactions with known cilia proteins: Aplnr, Casr, Gcgr, Grm6, Med1(or Mbd4), Mlh1, and Rxfp2." (PMID 36456625, 2022).
clear cell renal cell carcinomas (1 paper, 2020). "Hypermethylation of the CpG sites on GRM6 (glutamate metabotropic receptor 6) was reported to be a hallmark of CIMP in clear cell renal cell carcinomas." (PMID 32064261, 2020).
hemorrhagic disease (1 paper, 2021). Spontaneous or near spontaneous bleeding caused by a defect in clotting mechanisms (blood coagulation disorders) or another abnormality causing a structural flaw in the blood vessels (hemostatic disorders). "Most of these genes are known to be involved in the manifestation of various clinical phenotypes, such as metabolic diseases (CPT1B and BLVRA); hemorrhagic diseases (RUNX1 and GP6); and neuronal disorders (KCNAB3, FAM179B, CCDC60, GRM6, and PRDM8), among others." (PMID 34440289, 2021).
metastatic melanoma (1 paper, 2020). A melanoma that has spread from its primary site to another anatomic site. "Hypermethylation of GRM6 was detected in renal carcinoma, and LINGO3 was reported as one of the hub genes of metastatic melanoma." (PMID 32701143, 2020).
retinal disease (1 paper, 2015). "For example, in three cases, we identified potential new associations for mutations in retinal disease genes GPR98, CEP290 and GRM6 with an RP phenotype." (PMID 26667666, 2015).
tumor (2 papers, 2018 to 2025). "Other membrane proteins, such as GPCRs (e.g., GRM6, GPR37L1, NMUR2), are highly expressed to mediate growth and survival signaling, amplify tumor proliferation signals, and prevent apoptosis." (PMID 41440381, 2025).
GRM6 also shares sentences with these, for which no sentence is quoted: cancer (2 papers); night blindness (2); amyloidosis (1); brain injury (1); Marfan syndrome (1); melanoma (1); metabolic disease (1); Nystagmus (1); renal carcinoma (1); retinal disorder (1); retinal dystrophies (1); retinitis pigmentosa (1); retinoblastoma (1); Stickler syndrome (1).